THOP1 (thimet oligopeptidase 1)
Description:
Involved in the metabolism of neuropeptides under 20 amino acid residues long. Involved in cytoplasmic peptide degradation. Able to degrade the amyloid-beta precursor protein and generate amyloidogenic fragments. Also acts as a regulator of cannabinoid signaling pathway by mediating degradation of hemopressin, an antagonist peptide of the cannabinoid receptor CNR1 (By similarity).
Synonyms: EP24.15; MEPD_HUMAN; MP78; TOP
Tractability: Small molecule: it has a high-quality binding pocket. PROTAC: ubiquitination databases record sites on it; its protein half-life has been measured.
Target class: Enzyme; Hydrolase
Gene: Protein-coding gene on chromosome 19 (2,785,494 to 2,815,807, forward strand). Ensembl gene ENSG00000172009.
Subcellular location: Cytoplasm
Subcellular location (Human Protein Atlas): Cytosol
Pathways (Reactome):
Immune System: Antigen processing: Ubiquitination & Proteasome degradation
Gene Ontology:
Molecular function: protein binding; metalloendopeptidase activity; metallopeptidase activity
Biological process: protein polyubiquitination; proteolysis
Cellular component: cytosol; cytoplasm; mitochondrial intermembrane space
Genetic constraint (gnomAD): Loss-of-function variants: 50 observed, 72.25 expected, observed/expected ratio (o/e) 0.69, 90% interval 0.55 to 0.88. The upper end of that interval is the gene's LOEUF score, 0.88, which puts it in group 3 of 6, group 1 being the genes least tolerant of losing a copy. Missense variants: 843 observed, 970.88 expected, observed/expected ratio (o/e) 0.87, 90% interval 0.82 to 0.92. Synonymous variants: 426 observed, 418.6 expected, observed/expected ratio (o/e) 1.02, 90% interval 0.94 to 1.1.
Homologues: Orthologues: macaque THOP1 (97% identical), dog THOP1 (90% identical), mouse Thop1 (89% identical), rat Thop1 (89% identical), guinea pig THOP1 (87% identical), pig THOP1 (85% identical), zebrafish thop1 (74% identical), tropical clawed frog thop1 (72% identical), chimpanzee THOP1 (67% identical), Caenorhabditis elegans eelo-2 (21% identical), Drosophila melanogaster CG11771 (20% identical). Paralogues in human: NLN (62% identical), MIPEP (25% identical).
Diseases named in the same sentence as THOP1 in open-access papers:
THOP1 is named in the same sentence as 64 diseases in open-access papers, as found by Europe PMC text mining. Sharing a sentence is not in itself a finding about the gene and the disease. The quoted sentences say what the papers report.
Alzheimer disease (48 papers, 2011 to 2025). A progressive, neurodegenerative disease characterized by loss of function and death of nerve cells in several areas of the brain leading to loss of cognitive function such as memory and language. "THOP1 was associated with Alzheimer‘s disease (AD) as its mapping position on human chromosomes was reported to be within the linkage region for the late-onset AD2 locus on chromosome 19q13.3." (PMID 32847123, 2020). "The top Canonical Pathway for resistant strains, “Neuroprotective role of THOP1 in Alzheimer’s Disease,” is associated with enhanced protection against neurodegeneration and enrichment of this pathway in the resistant strains may explain the mild neurological symptoms observed in these mice." (PMID 34768809, 2021). "Interestingly, we found that two significantly enriched disease-associated pathways might be associated with T2DM (“neuroprotective role of THOP1 in Alzheimer’s disease” and “osteoarthritis pathway”)." (PMID 33329383, 2020). "THOP1 has a long and tumultuous history with late-onset Alzheimer’s disease (AD) dating from the 1990s." (PMID 40149871, 2025). "A surprising pathway we found associated with COVID-19 severity is the neuroprotective role of THOP1 in Alzheimer’s disease, however, recent studies have shown that Alzheimer’s-like signaling is occurring in the brains of COVID-19 patients." (PMID 37308820, 2023). "The “neuroprotective role of THOP1 in Alzheimer’s disease” pathway was primarily driven by increased expression of endonucleases and serine proteases." (PMID 38113112, 2023). "From the models, the most significant pathways are MODY signaling, the neuroprotective role of THOP1 in Alzheimer’s disease, and FXR/RXR Activation pathways." (PMID 37308820, 2023). "The final enriched pathway was the neuroprotective role of THOP1 in Alzheimer’s disease; this pathway has a strong correlation with lymphocyte levels and neutrophil percent." (PMID 35468151, 2022). "For resistant strains the most significant Canonical Pathway was “Neuroprotective Role of THOP1 [Thimet oligopeptidase] in Alzheimer’s Disease” (−log p = 2.59)." (PMID 34768809, 2021). "Based on IPA, only the “Neuroprotective Role of THOP1 in Alzheimer’s Disease” pathway was significant for the effect of WUR genotype within KS06-infected pigs." (PMID 33618723, 2021). "Specifically, the LXR/RXR activation, neuroprotective role for THOP1 in Alzheimer’s disease, and glutamate receptor signaling pathways were observed to be mostly downregulated in advanced cancer stage." (PMID 34966482, 2021). "Three of those pathways specifically the LXR/RXR activation, neuroprotective role for THOP1 in Alzheimer’s disease, and glutamate receptor signaling pathways, shift from being up- to mostly downregulated as approaching advanced cancer stage III." (PMID 34966482, 2021). "One canonical pathway, “Neuroprotective Role of THOP1 in Alzheimer’s Disease”, was marginally significantly enriched in humans (−log (p-value) = 1.35; p = 0.045) but not in mice (−log (p-value) = 0.796; p = 0.160)." (PMID 33260536, 2020). "Herein we also observed that the “neuroprotective role of THOP1 in Alzheimer’s disease” pathway was upregulated in the liver tissue of ZDF rats [Z-score = 2.45, −log(p) = 3.09], suggesting a neuroprotective role in T2DM progression." (PMID 33329383, 2020). "Top pathways in this tumor included caveolar-mediated endocytosis signaling and the neuroprotective role of THOP1 in Alzheimer’s disease." (PMID 31822682, 2019). "Top inhibited pathways in malignant cancers included intrinsic prothrombin activation pathway and neuroprotective role of THOP1 in Alzheimer’s disease." (PMID 30517191, 2018). "The most significantly enriched pathways for the different time points were G‐protein‐coupled receptor signaling (PND8), neuroprotective role of THOP1 in Alzheimer's disease (PND14), chondroitin sulfate degradation (Metazoa) (PND21), EIF2 signaling (PND35), and growth hormone signaling (PND70)." (PMID 40485115, 2025).
Alzheimer disease (continued). "Additionally, leading-edge gene THOP1 in the Alzheimer’s disease pathway, which is significantly enriched, is known to have a neuroprotective role." (PMID 37065470, 2023). "The first pathways we discuss which are not directly related to immune function are the LXR/RXR activation, FXR/RXR activation, atherosclerosis signaling, maturity-onset diabetes of young (MODY), and neuroprotective role of THOP1 in Alzheimer’s disease pathways." (PMID 37308820, 2023). "The elevated expression of thimet oligopeptidase (THOP1) is a neuroprotective response to amyloid-β (Aβ), a major component of Alzheimer’s disease plaques that may cause increased neuronal death." (PMID 37065470, 2023). "For six of these pathways IPA predicted decreased activity: CDC42 signaling, Sumoylation Pathway, Cell Cycle: G2/M DNA Damage Checkpoint Regulation, Neuroprotective Role of THOP1 in Alzheimer’s Disease, PD-1,PD-L1 cancer immunotherapy pathway and ILK Signaling." (PMID 36016386, 2022). "These contain the neuroprotective role of THOP1 in Alzheimer’s disease (P = 1.70 × 10−3)." (PMID 34470669, 2021). "The top predicted canonical pathways in the 30 ng/L treatment group were involved in S-methyl-5′-thioadenosine degradation II, cysteine biosynthesis/homocysteine degradation, neuroprotective role of THOP1 in Alzheimer’s disease, extrinsic prothrombin activation pathway, and coagulation system." (PMID 33807887, 2021). "These include the pathways known as the neuroprotective role of THOP1 in Alzheimer’s disease, synaptogenesis signaling pathway, neuroinflammation signaling pathway, endocannabinoid neuronal synapse pathway, synaptic long‐term depression, and neuropathic pain signaling in Dorsal horn neurons." (PMID 32920960, 2020). "Additionally, the core pathway enrichment analysis of ASS related proteins revealed that some proteins function as activators that are involved in the neuro-protective role of THOP1 signaling cascades in Alzheimer’s disease." (PMID 27296761, 2016). "However, the highest ratio (number of dysregulated genes/number of genes involved in the pathway) is found for the neuroprotective role of THOP1 in Alzheimer’s disease." (PMID 26932723, 2016). "In addition, regarding neurodegenerative diseases (NDDs), several functions, including Huntington’s disease signaling (EGFR, MAPK1, PSMB3), neuroprotection by THOP1 in Alzheimer’s disease (AGT, MAPK1) and Parkinson’s signaling (MAPK1), were activated only in aged mice." (PMID 38590360, 2024). "However, proteins in the other 4 networks are also involved in some of the canonical pathways; neuroprotective role of THOP1 in Alzheimer's disease, ERK5 signaling, and inhibition of ARE-mediated mRNA degradation pathway are among these pathways detected by IPA." (PMID 34658783, 2021). "Neuroprotective role of THOP1 in Alzheimer's disease and retinoic acid mediated apoptosis signaling were not significant at any of the individual time points examined." (PMID 21777430, 2011).
Obesity (4 papers, 2020 to 2023). Accumulation of substantial excess body fat. "Using this model, it was possible to investigate the potential functions of THOP1 on hyperlipidic diet-induced obesity (DIO) as well as some obesity-associated diseases such as insulin resistance." (PMID 32079362, 2020). "Altogether, the results presented herein successfully suggest THOP1 is a novel target for controlling obesity and associated diseases." (PMID 32079362, 2020). "Altogether, previous studies have suggested that THOP1 could be a therapeutic target for controlling obesity and associated diseases such as insulin resistance and NAFLD." (PMID 36979950, 2023). "However, while Nln-/- mice were shown herein to be more susceptible to diet-induced obesity, THOP1-/- mice were resistant to diet-induced obesity after being fed a HD for 24 weeks." (PMID 37894869, 2023). "Overall, we have, for the first time, successfully provided evidence that THOP1 could be a therapeutic target for controlling obesity and associated diseases, such as insulin resistance and NAFLS." (PMID 32079362, 2020). "Specific InPeps identified in the adipose tissue of HD-fed THOP1-/- mice were suggested to participate in the observed obesity-resistance phenotype." (PMID 37894869, 2023). "Further investigations are necessary to understand the molecular basis of the distinctive diet-induced obesity phenotype of Nln-/- and THOP1-/- animals." (PMID 37894869, 2023). "The adipose tissue expression of ADBR3 was higher in THOP1-/- male animals fed a HD, which distinctively from Nln-/- were resistant to diet-induced obesity." (PMID 37894869, 2023). "IDE predominantly metabolize peptides inside the cells, similarly to Nln and THOP1, corroborating previous suggestions that the intracellular peptide metabolism is modulated under a diet-induced obesity model." (PMID 37894869, 2023). "In a primate model of maternal obesity in which obesity was induced in baboons prior to pregnancy, THOP1 was identified as one of the five differentially expressed proteasome pathway genes targeted by four differentially expressed microRNAs." (PMID 32079362, 2020). "The physiological function of THOP1 on energy metabolism regulation was further investigated using a murine model of hyperlipidic (HD) diet-induced obesity (DIO) and insulin resistance." (PMID 32847123, 2020). "It has been suggested that the distinctive subcellular localization of Nln and THOP1 drives their biological significance, which, together with their biochemical specificities, could be of importance to the phenotype differences observed in diet-induced obesity." (PMID 37894869, 2023). "The present study aimed to investigate the possible function of THOP1 in the development of diet-induced obesity (DIO) and insulin resistance by utilizing a murine model of hyperlipidic DIO with both C57BL6 wild-type (WT) and THOP1 null (THOP1−/−) mice." (PMID 32079362, 2020). "Anorexigenic and orexigenic neuropeptides have not previously been characterized as THOP1 substrates and, here, the levels of hormonal peptides related to obesity were shown to be unaffected in THOP1−/− animals." (PMID 32079362, 2020).
glioma (3 papers, 2014 to 2022). A benign or malignant brain and spinal cord tumor that arises from glial cells (astrocytes, oligodendrocytes, ependymal cells). "THOP1 (as endo-oligopeptidase A-like, formerly EC 3.4.22.19) was reported secreting from glioma C6 cells and also from median eminence neurons." (PMID 32847123, 2020). "Cell fractionation studies have demonstrated that THOP1 is present in the particulate subcellular fractions of the central nervous tissue and secreted from distinctive cell lines, such as the rat glioma C6 and mouse AtT-20." (PMID 25180910, 2014). "Approximately 10% of the total cellular content of THOP1 from AtT20 or glioma C6 cells were released to the extracellular milieu, where the enzyme could be metabolizing neuropeptides either into a soluble or calcium-mediated membrane-bound form." (PMID 32847123, 2020).
Insulin resistance (3 papers, 2020 to 2023). Increased resistance towards insulin, that is, diminished effectiveness of insulin in reducing blood glucose levels. "Here, THOP1 was shown to play a key role in energy metabolism; THOP1−/− mice, distinctive from WT mice, were resistant to DIO and showed no insulin resistance after being fed a HD for 24 weeks." (PMID 32079362, 2020).
melanoma (3 papers, 2007 to 2020). A malignant, usually aggressive tumor composed of atypical, neoplastic melanocytes. "THOP1 was required, either together with nardilysin or alone, for the generation of a tumor-specific CTL epitope from PRAME, an immunodominant CTL epitope from Epstein–Barr virus protein EBNA3C, and a clinically important epitope from the melanoma protein MART-1." (PMID 31431000, 2019).
Sepsis (3 papers, 2019 to 2022). Sepsis is defined as life-threatening organ dysfunction caused by a dysregulated host response to infection. "Animals that survived from sepsis (3 WT and 4 THOP1-/-) were subjected to behavior tests in an open field arena at the 8th day." (PMID 31431000, 2019). "Here, a possible role of THOP1 in sepsis, another inflammatory condition with a high epidemiological burden, was identified." (PMID 31431000, 2019). "Here, we demonstrated that THOP1-/- mice have slightly better survival and behavior performance seven days after polymicrobial sepsis induction, with slightly lower expression of TLR4 and TNF-α in dorsal hippocampus." (PMID 31431000, 2019). "THOP1-/- mice also exhibit better survival and improved behavior in a sepsis model, but also a greater peripheral pain sensitivity measured in the hot plate test after bradykinin administration in the paw." (PMID 31431000, 2019). "Although there is no concrete evidence, neurolysin is hypothesized to be involved in the pathology of human diseases such as epilepsy, angiogenesis, tumor growth, sepsis, stroke, and metabolic disorder, together with thimet oligopeptidase (THOP1) and a POP." (PMID 35631755, 2022).
hepatocellular carcinoma (2 papers, 2014 to 2020). A malignant tumor that arises from hepatocytes. "Lower gene expression of THOP1 in the background liver of hepatocellular carcinoma (HCC) was also suggested to be a biomarker for risk of HCC development." (PMID 32847123, 2020). "Recent study demonstrated that high THOP1 mRNA expression level in the normal background liver of hepatocellular carcinoma (HCC) was significantly correlated with better survival." (PMID 25180910, 2014). "Moreover, high THOP1 mRNA expression in corresponding normal tissue of hepatocellular carcinoma (HCC) was correlated with a better overall survival." (PMID 25180910, 2014).
lung carcinoma (2 papers, 2014 to 2024). "THOP1, acting as an antagonist of BK, will likely reduce the likelihood of developing lung cancer by decreasing BK." (PMID 39668834, 2024).
non-small cell lung carcinoma (2 papers, 2014 to 2020). A group of at least three distinct histological types of lung cancer, including non-small cell squamous cell carcinoma, adenocarcinoma, and large cell carcinoma. "Low THOP1 gene expression was suggested to have clinical potential as a biomarker for better survival prognostic of patients diagnosticated with non-small cell lung cancer (NSCLC)." (PMID 32847123, 2020).
oral cancer (2 papers, 2022 to 2025). "Transcriptome analysis suggested that miRNA-1307-5p could promote oral cancer progression by suppressing THOP1, EHF, RNF4, GET4 and RNF114." (PMID 36142544, 2022). "Interestingly, to the best of our knowledge, apart from EHF, no studies have reported the association of THOP1, RNF4, GET4 and RNF114 with oral cancers." (PMID 36142544, 2022).
rheumatoid arthritis (2 papers, 2019 to 2020). A chronic, systemic autoimmune disorder characterized by inflammation in the synovial membranes and articular surfaces. "THOP1 has been implicated in rheumatoid arthritis (RA), another common autoimmune disease manifesting as chronic inflammation of the joints and characterized by a significant genetic contribution." (PMID 31431000, 2019). "Previous genetic association studies integrated with gene expression and pathway analyses identified THOP1 as a relevant protein for the development of rheumatoid arthritis (RA)." (PMID 32847123, 2020).
Anxiety (1 paper, 2019). Intense feelings of nervousness, tension, or panic often arise in response to interpersonal stresses. "The elevated plus maze task suggested no signs of altered anxiety behavior of THOP1-/- compared to WT mice." (PMID 31431000, 2019).
Autoimmunity (1 paper, 2019). The occurrence of an immune reaction against the organism's own cells or tissues. "Altogether, these data supports that THOP1 may be involved in neurodegeneration and autoimmunity." (PMID 31431000, 2019).
bipolar disorder (1 paper, 2015). A disorder of the brain that causes unusual shifts in mood, energy, activity levels and the ability to carry out day-to-day tasks. "We identified three rare deletions in KCNJ6, UNC13C, OTOL1 and 7 rare duplications in CNTNAP2/MIR548F3, CORO7/VASN, DTNB, EMID2, KCNF1, PDPR and SGTA/THOP1 that are present in children with bipolar disorder (and their parents)." (PMID 25887117, 2015).
demyelinating disorder (1 paper, 2019). "THOP1 gene suppression strongly affected the clinical performance of mice in experimental EAE: an animal model of multiple sclerosis, a chronic neuroinflammatory demyelinating disorder of the CNS with a marked neurodegenerative component initiated by CD4+ T cells." (PMID 31431000, 2019).